TNF (tumor necrosis factor)
Diseases named in the same sentence as TNF in open-access papers (continued):
Sharing a sentence is not in itself a finding about the gene and the disease.
COVID-19 (continued). "If so, the cross-talk among MMPs, TNF-α, and AMPK is a candidate therapeutic target to mitigate the metabolic damage associated with COVID-19." (PMID 33800947, 2021). "Significantly elevated levels of IL-6 and TNF-α are correlated with COVID-19 severity, and the concentration of IL-6 in COVID-19 patients is linked to the tryptophan metabolism into the kynurenine pathway." (PMID 34803442, 2021). "Further, regulation of levels of IL-6 and TNF-α suggest possible regulation of inflammation, as “cytokine storm” plays an important role during severe COVID-19." (PMID 34001247, 2021). "Our results suggest that interleukin, TLR, TNF, renin-angiotensin, Fc epsilon RI, insulin signaling, PI3K–Akt signaling pathway, and MAPK signaling are partially shared between COVID-19 and its associated comorbidities." (PMID 34067609, 2021). "GCSF, IL-1RA, IL-6, IL-8, IL-10, IL-12 (p40), MCP-1, M-CSF, and TNF-α were correlated with SOFA scores in COVID-19 patients and controls, with increased cytokine expression positively correlating with higher SOFA scores." (PMID 34131192, 2021). "For instance, we found that TNF-α levels were lower in the serum of COVID-19 patients as compared to pandemic influenza A(H1N1) patients." (PMID 33995342, 2021). "In conjunction, a broad range of TNF inhibitor formulations are currently being used, particularly humanized TNF-α-inhibitors, namely adalimumab and infliximab, to treat COVID-19 and ameliorate cytokine storm." (PMID 33946736, 2021). "Similar to TNF-α, the mean serum levels of IL-17 in the patients with COVID-19 were significantly higher than those observed in the control group." (PMID 34938746, 2021). "During the pandemic, anti-TNF therapy has been studied for its potential as a treatment for COVID-19 besides the anti-IL-6 receptor therapy." (PMID 35054223, 2021). "Three BIMs: MAP2, NSE and S100B, two EIMs: sICAM1 and sVCAM1 and seven CCs: GRO IL10, sCD40L, IP10, IL1Ra, MCP1 and TNFα were significantly (p < 0.05) elevated in the COVID-19 cohort compared to controls." (PMID 34838058, 2021). "An elevated level of cytokines, such as interleukin (IL)-1, IL-2, IL-6, IL-8, IL-10, TNF-α, and soluble IL-2R, and a sharp inflammatory storm have been reported in patients with severe COVID-19 by our team and other researchers." (PMID 33776910, 2021). "Altogether, these data suggest that the severity of COVID-19 may be associated with inflammasome activation in monocytes that results in large amounts of IL-1ß and generates an excessive inflammatory response, further characterized by high levels of IL-6 and TNF-α." (PMID 33649297, 2021). "A hyper-inflammatory response, which presents as a cytokine storm, exacerbates COVID-19 severity with high levels of serum IL-6, IL-8, TNF-α, and IL-1β, thus indicating low chances of patient survival." (PMID 33800947, 2021). "Individuals with COVID-19 have been reported to have high levels of major inflammatory cytokines such as IL-6, IL-1β, and TNF-α in the circulation, which was associated with the magnitude of disease severity." (PMID 33959020, 2021). "Other possible explanations for our findings include the consequences of non-TNF inhibitor immunosuppressive medications for COVID-19 outcomes." (PMID 34661663, 2021). "We demonstrated that the CXCL10+ CCL2+ macrophages are transcriptionally similar to human blood-derived macrophages stimulated by IFN-γ and TNF-α and were expanded in severe COVID-19 lungs and inflamed RA, CD, and UC tissues." (PMID 33879239, 2021). "Severe COVID-19 cases had elevated the levels of various cytokines, including granulocyte colony stimulating factor, IL-10, TNF-α, MIP-1α and MCP-1." (PMID 34064802, 2021). "Being that inflammasome activity is dysregulated in COVID-19, following the infection, alveolar macrophages secrete TNF-α and IL-1β, giving rise to cell death, damage, and NLRP3 activation that trigger the acute proinflammatory cascade." (PMID 33916409, 2021).
COVID-19 (continued). "For example, the drug thalidomide, inhibiting NFkB and TNF, was reported as potential treatment for COVID-19." (PMID 33413329, 2021). "A case report on using the anti-TNF-α antibody for treating COVID-19 pneumonia and severe ulcerative colitis suggested that anti-TNF-α agents are an effective and safe therapy for COVID-19." (PMID 34725309, 2021). "CRP was positively associated with IFNγ, IL-2, TNFα IL-1α IFNβ IL-6 IL-17A IL-10, CXCL-10 and VEGF in children with PIMS-TS and COVID-19." (PMID 33813138, 2021). "In another study, T cell numbers in COVID-19 patients were negatively correlated with patient survival and with serum IL-6, IL-10, and TNF-α concentrations." (PMID 33445583, 2021). "Our data also support the use of specific NLRP3 inhibitors, such as MCC950, to attenuate inflammasome-related responses during COVID-19, since this drug was able to abrogate ex-vivo IL-1β secretion, conversely to colchicine, which decreased TNF-α release." (PMID 35095880, 2021). "The IHC analysis showed increased expression of caspase-1, ICAM-1, IL-1β, IL-6, MMP-9, TNF-α, and other markers in the hearts of COVID-19 patients." (PMID 34804033, 2021). "Among cytokines, IL-6 and TNF-α levels at the time of hospitalization were reported to be independent predictors of disease severity and death in hospitalized patients with COVID-19." (PMID 34769508, 2021). "Previous studies have found an association between an increase in levels of IL-2, IL-6, IL-7, IL-10 and TNF-α and the severity or mortality of COVID-19." (PMID 34490065, 2021). "Pro-inflammatory cytokines and chemokines (IL-6, IL-8, TNF-α, IL-1β) are differentially expressed in COVID-19 patients according to severity." (PMID 34320031, 2021). "More than half of ARDS in all COVID-19 patients manifested macrophage activation syndrome with high levels of TNF and IL-6 in the circulation." (PMID 33907514, 2021). "Namely, the four main cytokines/chemokines detected in the blood of COVID-19 patients were analyzed: IL-6, IL-17, TNFα, and GM-CSF." (PMID 34248910, 2021). "Elevated circulating blood levels of the inflammatory cytokine, TNF-α have been described in the cytokine milieu of patients with cardiovascular disease and in those with COVID-19." (PMID 34835015, 2021). "Such MDSCs have been shown to exhibit enhanced immunosuppressive activity by suppressing T-cell proliferation and function, as well as increased IFN-γ and TNF-a production, probably contributing to a form of immune-paralysis observed in COVID-19 patients." (PMID 34512643, 2021). "In terms of laboratory parameters, elevated inflammatory cytokines and infection-related factors, such as TNF-α, IL-6, IL-10, IL-8, IL-1β, IL-2R, ferritin, hs-CRP and procalcitonin were significantly associated with higher death risk of COVID-19." (PMID 34521370, 2021). "It was reported significantly increased plasma levels of pro-inflammatory cytokines, including IL-1β, IL-6, IL-7, IL-8, IL-9, IL-10, interferon (IFN)-γ, and TNF-α in patients with COVID-19 than in healthy adults, but similar levels of IL-5, IL12p70, and IL-15." (PMID 34595175, 2021). "Anti-TNF drugs that are given priority for repurposing in COVID-19 management and anti-INSR therapy need to be re-evaluated due to conflicting reports." (PMID 34067609, 2021). "Isolated circulating monocytes from acute COVID-19 patients showed a sustained production of IL-6 and tumor necrosis factor (TNF)-α." (PMID 34572439, 2021). "Our data provide evidence that in the presence of TNF-α, S1 enhanced expression of the endothelial cell adhesion markers in vitro and is consistent with the hypothesis that the presence of pro-inflammatory cytokines and chemokines increase the risk of poorer outcome with COVID-19." (PMID 34835015, 2021). "Compared to mild cases, patients with severe COVID-19 have markedly increased levels of pro-inflammatory cytokines, including IL-1, IL-2, IL-6, IL-8, IL-10, IL-12, IL-17, tumor necrosis factor (TNF)-α and IFN-γ." (PMID 33935986, 2021).
COVID-19 (continued). "Conversely, the frequencies of CD4+ effector cells differed: the amount of specific AIM+IFNγ+ and AIM+IFNγ+IL-2+TNFα+ (triple+) CD4+ T cells were lower in COVID-19-naive older participants than in COVID-19-naive young adults." (PMID 34868051, 2021). "Further, as demonstrated by our results, heightened TNF-α production was indicative of severe disease progression in COVID-19 patients." (PMID 34131192, 2021). "After 6 or 24 h of honeysuckle or Huangqi treatment, the cell medium was collected to quantify the secretion level of IL-6 and TNF-α, two of the most abundantly detected cytokines in COVID-19 patients’ plasma." (PMID 35401158, 2021). "Susceptibility of these four major genes such as ACE2, IL-2, 7 and 10, TNF, and VEGF is associated with COVID-19." (PMID 33907373, 2021). "Our SpA patients with documented COVID-19 were both on anti-TNFα therapy, and indeed -as mentioned- their disease course was mild, with symptoms like fever, malaise, myalgia, lasting only about a week." (PMID 34177927, 2021). "Well known that TNF-α, performing as a megaphone of inflammation, is crucial in nearly all kinds of acute inflammatory responses, including COVID-19." (PMID 34177566, 2021). "In the PsoProtect study, patients with psoriasis taking TNF inhibitors also demonstrated more favorable outcomes from COVID-19, and similar trends were noted in the SECURE-IBD registry." (PMID 33969248, 2021). "The concentration of sTNF-RI and TNF-α in COVID-19 patients and healthy subjects according to ICU status." (PMID 33968010, 2021). "For example, synergism of interferon-gamma and tumor necrosis factor-mediated signaling can perpetuate a COVID-19-induced cytokine storm by stimulating programmed cell death (apoptosis and necroptosis) and increasing mortality." (PMID 34975885, 2021). "According to relevant mouse studies in vitro and in vivo, synergistic activity of IFN-γ and TNF-α mimics the symptoms of COVID-19 and triggers robust cell death." (PMID 34394108, 2021). "The majority of respondents would pause TNF-alpha inhibitors and IL-12/23-inhibitors in COVID-19 patients." (PMID 33683393, 2021). "Although anti-TNF treatment was suggested as a potential treatment for COVID-19, insufficient data exists to support the use of anti-TNF therapy because reports indicate diverse efficiency." (PMID 34445140, 2021). "A higher amount of proinflammatory cytokines (TNF-alpha, IL-1, IL-6) and chemokines were noted in patients with severe COVID-19 findings compared to patients with mild symptoms." (PMID 33641314, 2021). "Specifically, minocycline is effective in reducing COVID-19–related complications, through attenuation of cytokine storm as apparent by reduction of interleukin (IL)-6, IL-1, and tumor necrosis factor (TNF)-α." (PMID 33967777, 2021). "As expected, the magnitude of IFNγ, IL-2 and TNF producing effector cells was significantly elevated in COVID-19 patients." (PMID 34228322, 2021). "Patients with severe COVID-19 show increased levels of IL-6, IL-8, IL-10, IL-2R, and tumor necrosis factor (TNF)-α compared to those with mild to moderate disease." (PMID 34315546, 2021). "An attempt to correlate serum cytokine concentrations for over 1500 COVID-19 hospitalized patients with disease outcomes revealed that levels of IL-6, IL-8, and TNF correlated with disease outcome and mortality." (PMID 33445583, 2021). "As another example, monitoring of COVID-19-associated CRS patient cytokine profiles in 2019 revealed higher levels of IL-2, IL-7, IL-10, G-SCF, MCP-1, MIP-1α, and TNF-α in plasma of intensive care unit (ICU) patients versus plasma of non-ICU patients." (PMID 34884813, 2021). "Several cytokines including interleukin (IL)-6, IL-10, interferon-γ (IFN-γ), and tumor necrosis factor-α (TNF-α) have been observed to increase dramatically during acute infection in COVID-19 patients." (PMID 34307393, 2021). "Plasma IL-6 and TNF-α levels were significantly higher in COVID-19 patients and active AOSD patients than in HC." (PMID 34367188, 2021).
COVID-19 (continued). "Of note, neutralizers of IL17, IL6, IL1, IFNA, IFNG, and TNF were predicted as antagonists of COVID-19 biology." (PMID 33782412, 2021). "A proteomic study comparing HDL proteins of critically ill COVID-19 patients showed both a rise in SAA family proteins and HDL that were unable to inhibit apoptosis caused by tumor necrosis factor α in endothelial cells." (PMID 34945250, 2021). "The other paper reported that COVID-19 patients have lower lymphocyte counts and increased interleukin (e.g., IL-6) and TNF-α levels compared with the healthy cohort." (PMID 34161373, 2021). "We proposed a three-variable (NLR, Spo2/Fio2 ratio, and LDH) and four-variable model (NLR, Spo2/Fio2 ratio, LDH, and TNF-α) for identifying the hyperactive phenotype of COVID-19." (PMID 34150812, 2021). "We also observed the upregulation of IFN-γ, CCL2, IL-8, IL-12p70, IL-17a and TNF-α in COVID-19 patients compared to healthy controls." (PMID 34386007, 2021). "An excessive amount of pro-inflammatory cytokines, including tumor necrosis factor-alpha (TNF-α), interleukin (IL)-1β, and IL-6, has been reported in most COVID-19 patients." (PMID 33708378, 2021). "IL-6 and TNF-α serum levels remained independent and significant predictors of disease severity and deaths of COVID-19 patients." (PMID 34834033, 2021). "Excessive production and release of cytokines such as tumor necrosis factor (TNF), interleukin (IL)-1, and IL-6 are characteristic of COVID-19." (PMID 34094634, 2021). "Pathway analysis between Ephedra-Glycyrrhiza and COVID-19 showed that the key targets were TNF-α, IL2, FOS, ALB, and PTGS2." (PMID 33581688, 2021). "It has been shown that capillary leak, the major factor deteriorating lung function in patients with COVID-19, is driven by TNF-α, IL-1A, and IL-6 inflammatory cytokines." (PMID 33995033, 2021). "Multiple studies have also demonstrated elevation of additional inflammatory markers such as IL-6, IL-8, IL-10, and TNF-α in COVID-19 patients." (PMID 33996864, 2021). "Tumor necrosis factor (TNF) is another key proinflammatory cytokine involved in COVID-19 hyperinflammation, as COVID-19 patients have increased TNF concentrations." (PMID 34975885, 2021). "Many anti-rheumatic treatments have been extensively evaluated for their efficacy of treating COVID-19 in RADs patients, with TNF-α inhibitors and IL-6 receptor antagonist receiving more positive reviews." (PMID 34490312, 2021). "The analysis of the immune characteristics of patients with severe COVID-19 revealed significantly upregulated levels of cytokines, including IL-6, TNF-α, IL-1β, and IL-8, among others." (PMID 34360706, 2021). "Patients with severe COVID-19 showed elevated levels of galectin-3, tumor necrosis factor, IL-1, and IL6, compared to those with moderate disease or normal subjects." (PMID 34205807, 2021). "Human cells respond to infection by SARS-CoV-2, the virus that causes COVID-19, by producing cytokines including type I and III interferons (IFNs) and proinflammatory factors such as IL6 and TNF." (PMID 34211037, 2021). "Combined analyses of all measured cytokines (IL-2, IFN-γ, and TNF-α) showed that the overall polyfunctional profile of SARS-CoV-2–specific cells in COVID-19 participants was distinct from uninfected controls (P < 0.0001)." (PMID 33945513, 2021). "An observational study illustrated that metformin reduces the mortality rate in DM patients with severe COVID-19, more evident in women than men, through the suppression of TNF-α synthesis and release." (PMID 34124187, 2021). "Using previously published data of the critically ill COVID-19 patients, we found that IL-17 levels positively correlated with tumor necrosis factor α (TNF-α) levels (rs = 0.33, p = 0.049)." (PMID 34575667, 2021). "In female COVID-19 patients, TNF-α levels were higher in those with high SOFA scores compared to those with low SOFA scores (p = 0.0476)." (PMID 34402750, 2021).
COVID-19 (continued). "Although the profile of inflammatory markers is highly variable between patients, a general phenotype of severe COVID-19 is characterized by elevated IL-6, IL-8, IL-10, TNF-alpha, CCL2, CCL3, and CXCL8." (PMID 34830356, 2021). "Obesity is characterized by a chronic low state of inflammation and cytokines produced in adipose tissue (TNF-α, IL1β, IL-6 and IL-15) are similar to those involved in COVID-19." (PMID 33890193, 2021). "A clinical trial using Certolizumab pegol (a TNF blocker) along with antiviral therapies can have beneficial effects in patients with COVID-19." (PMID 33937545, 2021). "From the KEGG enrichment analysis, our results indicated that the key signaling pathways of AE against COVID-19 are TNF, TLR, HIF-1 and NLRs, which are closely related to inflammation, immunity and oxidation process." (PMID 33658066, 2021). "Analysis revealed a stronger positive correlation between the serum values of IL-33 and TNF-α (p = 0.000), IL-1β (p = 0.000), IL-6 (p = 0.000), IL-12 (p = 0.000), and IL-23 (p = 0.000) in COVID-19 patients with severe disease." (PMID 34917631, 2021). "Although appropriate levels of proinflammatory cytokines are required to activate immune cells involved in viral control, extremely high levels of IL-1β, IL-10, G-CSF, GM-CSF, IFN-γ and TNF-α were detected in COVID-19 patients." (PMID 34439920, 2021). "In patients with severe COVID-19, we found that TNF-α was satisfactorily correlated with IL-2, IL-4, and IFN-γ, and monocytes were negatively correlated with IL-2, IL-4, and TNF-α." (PMID 34712741, 2021). "Usually, patients who have COVID-19 have a decreased number of helper T cells, cytotoxic T cells, regulatory T cells, and natural killer (NK) cells, but increased leptin, TNF-α, interleukin-1 (IL-1), interleukin-2 (IL-2), and interferon-gamma (IFN-γ)." (PMID 34064950, 2021). "It is possible that addition of TNF-alpha inhibitors at COVID-19 diagnosis decreases hospitalization rate." (PMID 34336892, 2021). "Dexamethasone inhibits IL-1 and TNF activity in the lung fibroblasts and, thus, reduces lung fibrosis, a common COVID-19 complication." (PMID 34017839, 2021). "Coupled with the high IL-6, IL-10, and TNF levels, lymphopenia was observed in severe COVID-19 manifestations." (PMID 34912345, 2021). "The cytokine profile of HLH is characterized by high levels of IFN-γ, TNF-α, IL-6, IL-10, and IL-12, a similar pattern to what is found in severe COVID-19." (PMID 33557908, 2021). "Two off-patent anti-TNF agents, infliximab and adalimumab, are currently undergoing clinical trials for COVID-19 treatment." (PMID 33714258, 2021). "According to a study by Min, 308 patients with COVID-19 showed that severe cases had a higher level of proinflammatory factors at admissions such as IL-2R, IL-6, IL-8, IL-10, and TNF-α." (PMID 34970527, 2021). "The article has highlighted that the pathophysiology of the COVID-19 cannot be explained solely on the basis of the increase in a few inflammatory cytokines such as IL-6 and TNF." (PMID 34373466, 2021). "In the setting of a more severe COVID-19 illness, these pro-inflammatory cytokines IL-6, IL-2 and TNF-α are released resulting in a cytokine release syndrome, and trigger myocardial inflammation." (PMID 33034203, 2021). "The IFNα/β response is one of multiple responses, including production of IL-6, TNFα, and IL-1b, by innate and adaptive immune cells that have the potential to limit COVID-19 progression." (PMID 34368185, 2021). "Patients with severe COVID-19 had significantly higher Gal-3, TNF-α, IL-1β, and IL-6 than those with moderate disease." (PMID 34367188, 2021). "Clinical experiences with TNF inhibitor for COVID-19 have been reported with infliximab, a monoclonal antibody against TNF, only." (PMID 34959657, 2021).